ENSG00000249590 (novel SEC14-like 2 (S. cerevisiae) (SEC14L2) and mitochondrial protein 18 kDa (MTP18) protein)
Gene: Protein-coding gene on chromosome 22 (30,409,255 to 30,428,990, forward strand). Ensembl gene ENSG00000249590.
Genetic constraint (gnomAD): Loss-of-function variants: 40 observed, 41.47 expected, observed/expected ratio (o/e) 0.96, 90% interval 0.75 to 1.26. Missense variants: 391 observed, 460.59 expected, observed/expected ratio (o/e) 0.85, 90% interval 0.78 to 0.92. Synonymous variants: 150 observed, 176.77 expected, observed/expected ratio (o/e) 0.85, 90% interval 0.74 to 0.97.